FZR1 (fizzy and cell division cycle 20 related 1)
Description:
Substrate-specific adapter for the anaphase promoting complex/cyclosome (APC/C) E3 ubiquitin-protein ligase complex. Associates with the APC/C in late mitosis, in replacement of CDC20, and activates the APC/C during anaphase and telophase. The APC/C remains active in degrading substrates to ensure that positive regulators of the cell cycle do not accumulate prematurely. At the G1/S transition FZR1 is phosphorylated, leading to its dissociation from the APC/C. Following DNA damage, it is required for the G2 DNA damage checkpoint: its dephosphorylation and reassociation with the APC/C leads to the ubiquitination of PLK1, preventing entry into mitosis. Acts as an adapter for APC/C to target the DNA-end resection factor RBBP8/CtIP for ubiquitination and subsequent proteasomal degradation. Through the regulation of RBBP8/CtIP protein turnover, may play a role in DNA damage response, favoring DNA double-strand repair through error-prone non-homologous end joining (NHEJ) over error-free, RBBP8-mediated homologous recombination (HR).
Synonyms: Fzr; hCDH1; CDH1; KIAA1242; HCDH; FZR2; CDC20C; DEE109
Tractability: PROTAC: UniProt records ubiquitination sites on it; ubiquitination databases record sites on it.
Gene: Protein-coding gene on chromosome 19 (3,506,277 to 3,538,334, forward strand). Ensembl gene ENSG00000105325.
Subcellular location: Nucleus (Isoform 2); Cytoplasm (Isoform 3)
Subcellular location (Human Protein Atlas): Nuclear membrane; Nucleoplasm
Pathways (Reactome):
Cell Cycle: APC/C:Cdh1 mediated degradation of Cdc20 and other APC/C:Cdh1 targeted proteins in late mitosis/early G1; Autodegradation of Cdh1 by Cdh1:APC/C; Conversion from APC/C:Cdc20 to APC/C:Cdh1 in late anaphase; Cyclin A/B1/B2 associated events during G2/M transition; Cyclin A:Cdk2-associated events at S phase entry; Phosphorylation of Emi1; Regulation of APC/C activators between G1/S and early anaphase; SCF-beta-TrCP mediated degradation of Emi1
DNA Replication: Assembly of the pre-replicative complex; CDK-mediated phosphorylation and removal of Cdc6
Cellular responses to stimuli: Senescence-Associated Secretory Phenotype (SASP)
Disease: Aberrant regulation of mitotic exit in cancer due to RB1 defects
Gene expression (Transcription): Transcriptional Regulation by VENTX
Immune System: Antigen processing: Ubiquitination & Proteasome degradation
Gene Ontology:
Molecular function: protein binding; ubiquitin-like ligase-substrate adaptor activity; anaphase-promoting complex binding; ubiquitin ligase activator activity; ubiquitin-protein transferase activator activity
Biological process: anaphase-promoting complex-dependent catabolic process; mitotic G2 DNA damage checkpoint signaling; positive regulation of ubiquitin protein ligase activity; negative regulation of cellular senescence; positive regulation of anaphase-promoting complex-dependent catabolic process; protein K11-linked ubiquitination; regulation of meiotic cell cycle; regulation of mitotic cell cycle; positive regulation of cell population proliferation; protein ubiquitination
Cellular component: nuclear membrane; nucleoplasm; nucleus; anaphase-promoting complex; cytosol; cytoplasm
Genetic constraint (gnomAD): Loss-of-function variants: 9 observed, 46.65 expected, observed/expected ratio (o/e) 0.19, 90% interval 0.12 to 0.34. The upper end of that interval is the gene's LOEUF score, 0.34, which puts it in group 1 of 6, group 1 being the genes least tolerant of losing a copy. Missense variants: 406 observed, 609.56 expected, observed/expected ratio (o/e) 0.67, 90% interval 0.61 to 0.72. Synonymous variants: 314 observed, 275.15 expected, observed/expected ratio (o/e) 1.14, 90% interval 1.04 to 1.25.
Homologues: Orthologues: chimpanzee FZR1 (100% identical), macaque FZR1 (100% identical), guinea pig FZR1 (99% identical), pig FZR1 (99% identical), mouse Fzr1 (98% identical), rat Fzr1 (98% identical), zebrafish fzr1a (92% identical), tropical clawed frog fzr1 (89% identical), rabbit FZR1 (71% identical), Drosophila melanogaster fzr (69% identical), Caenorhabditis elegans fzr-1 (57% identical). Paralogues in human: CDC20 (39% identical), CDC20B (26% identical).
Diseases named in the same sentence as FZR1 in open-access papers:
FZR1 is named in the same sentence as 33 diseases in open-access papers, as found by Europe PMC text mining. Sharing a sentence is not in itself a finding about the gene and the disease. The quoted sentences say what the papers report.
breast carcinoma (5 papers, 2015 to 2022). "IHC staining was conducted to identify the expression of FZR1 on the samples of formalin-fixed paraffin embedded breast cancer tissues." (PMID 35877249, 2022). "Our results suggested that FZR1 can be a potential biomarker of NACT in breast cancer and is involved in the regulation of chemotherapy drugs induced apoptosis." (PMID 32978372, 2020). "In this study, we identified that FZR1 can be a novel biomarker for breast cancer neoadjuvant chemotherapy according to clinical patient cohort evaluation and molecular mechanism investigation." (PMID 32978372, 2020). "Recently reported that knockdown FZR1 and Rb in human breast cancer cells promote cell division arrest by CDK4/6-specific inhibitor Palbociclib (PD0332991) treatment." (PMID 32978372, 2020). "In this study, we identified that FZR1 as a biomarker for breast cancer NACT based on the transcriptomic data analysis and the molecular mechanism investigation." (PMID 32978372, 2020). "To obtain more benefit for breast cancer patient, we propose that the FZR1 IHC score using at the clinical to predict the effect of neoadjuvant chemotherapy." (PMID 32978372, 2020). "Taken together, our results demonstrated that FZR1 can be a potential biomarker for NACT in breast cancer." (PMID 32978372, 2020). "Our investigation revealed that FZR1 can be a potential biomarker for breast cancer NACT prediction through regulating apoptosis and cell cycle arrest." (PMID 32978372, 2020). "Our analysis identified FZR1 as a biomarker of NACT for breast cancer regulating apoptosis and cell cycle arrest." (PMID 32978372, 2020). "We also confirmed that overexpression FZR1 promotes chemotherapy drug induced apoptosis in MBA-MD-231 breast cancer cell line." (PMID 32978372, 2020). "In human breast cancer cells, simultaneous knockdown of Rb and FZR1 synergistically bypasses cell division arrest induced by the CDK4/6-specific inhibitor PD-0332991." (PMID 25562820, 2015). "Importantly, we also observed synergy between Rb and FZR1 knockdown in bypassing the proliferation arrest induced by treatment of human breast cancer cells with the CDK4/6 inhibitor PD-0332991." (PMID 25562820, 2015). "Patients with either high levels of HLA-DR or TILs, or high activation score of MHC-II, or low level of CD163+ TAMs, as well as high expression level of FZR1, had better response to NACT in breast cancer." (PMID 35877249, 2022). "To test this possibility, we combined treatment of human breast cancer cells with the CDK4/6-specific inhibitor PD-0332991 with knockdown of Rb and FZR1." (PMID 25562820, 2015). "We found that combined inhibition of the Rb transcriptional repressor and the FZR1 APC/C co-activator eliminates the normal requirement for CDK4/6-cyclin D kinase activity in C. elegans and human breast cancer cells." (PMID 25562820, 2015). "FBXO1 was negatively regulated by the E3 ligase (FZR1) and the co-regulator of E3 ligase (FBXL8), which were known to play an oncogenic role in breast cancer, and FBXO1 could inhibit the expression of ribonucleotide reductase M2 (RRM2), a pro-tumorigenic protein." (PMID 35046938, 2021).
aplastic anemia (2 papers, 2023). Anemia resulting from bone marrow failure (aplastic or hypoplastic bone marrow). "For instance, the ubiquitin ligase STUB1 regulates the stability and activity of RUNX1 in leukemia; RNF38 promotes RUNX1 ubiquitination and enhances RUNX1-mediated erythroid transcriptional program inhibition; while FZR1 regulates ubiquitin-dependent degradation of RUNX1 in aplastic anemia." (PMID 36949071, 2023).
colorectal cancer (2 papers, 2020 to 2022). A primary or metastatic malignant neoplasm that affects the colon or rectum. "The evidence showed that FZR1 interacted with PRL-3 to regulate the progression of colorectal cancer by controlling the stability of AURKA49." (PMID 32978372, 2020).
breast tumors (1 paper, 2011). "Twenty-four (49.0%) of the 49 dysregulated genes were significantly upregulated in the 23 DNA aneuploid breast tumors relative to the DNA diploid breast tumors, while only one gene (FZR1) among the 49 dysregulated genes was significantly down-regulated (P < 0.05)." (PMID 21352579, 2011).
cervical cancer (1 paper, 2022). A primary or metastatic malignant neoplasm involving the cervix. "Univariate Cox regression analysis screened 7 genes (FZR1, IMPDH1, HNRNPCL2, PCNA, GPKOW, XPA, and DDX39A) that were associated with the cervical cancer prognosis." (PMID 35909901, 2022). "Identification of KIN-related prognostic genes in cervical cancer revealed that a total of 5 genes (FZR1, IMPDH1, GPKOW, XPA, and DDX39A) were constructed for this risk score, and the results showed that CTLA4 expressions were negatively correlated with the risk score." (PMID 35909901, 2022).
colorectal tumour (1 paper, 2016). "Human colorectal tumour arrays show higher percentage of SKP2 positive samples and lower percentage of FZR1 and p27KIP1 positive samples and high FZR1 expression was associated with tumours showing lower grade histology." (PMID 27402801, 2016).
epilepsy (1 paper, 2019). A brain disorder characterized by episodes of abnormally increased neuronal discharge resulting in transient episodes of sensory or motor neurological dysfunction, or psychic dysfunction. "In conclusion, here we describe a new pathology characterized by antenatal microcephaly, psychomotor retardation, and severe epilepsy, secondary to heterozygous mutations of the Fzr1 gene." (PMID 31318984, 2019). "Here, we describe a de novo missense mutation (c.560A>G) in the human Fzr1 gene that predicts an aspartate‐to‐glycine substitution (p.Asp187Gly) in the Cdh1 protein, which results in prenatal microcephaly, psychomotor retardation, and severe epilepsy." (PMID 31318984, 2019). "We now identified a novel missense mutation (c.560A>G) in the human Fzr1 gene, that predicts an aspartate‐to‐glycine substitution (p.Asp187Gly), which results in severe psychomotor retardation, microcephaly, and refractory epilepsy." (PMID 31318984, 2019). "Hence, we have identified a de novo mutation in the human Fzr1 gene that results in prenatal microcephaly, refractory epilepsy, and psychomotor retardation." (PMID 31318984, 2019).
Epileptic encephalopathy (1 paper, 2019). A condition in which epileptiform abnormalities are believed to contribute to the progressive disturbance in cerebral function. "The role of the Fzr1 gene, as well as the existence of antenatal microcephaly, broadens the genotype and phenotype of this epileptic encephalopathy, providing added value to our findings." (PMID 31318984, 2019).
Infertility (1 paper, 2020). "While the control WT Fzr1+/+ and Fzr1Gt wt/Gt wt KI males produced normal size of litters over this period, the Fzr19A/9A KI males showed infertility over a period of 4 months." (PMID 32572094, 2020). "Since the control Fzr1Gt wt/Gt wt KI mice showed normal fertility, it is tenable that the infertility in the Fzr19A/9A KI males was attributed to the introduction of non-phosphorylatable mutations in FZR1." (PMID 32572094, 2020). "Thus the infertility caused by non-phosphorylatable mutations in FZR1 was male specific." (PMID 32572094, 2020).
melanoma (1 paper, 2019). A malignant, usually aggressive tumor composed of atypical, neoplastic melanocytes. "We have recently reported that FZR1 promotes BRAF ubiquitination and subsequent proteolysis in normal melanocytes, whereas this process is inhibited in melanoma cells due to inhibitory phosphorylations by ERK and CDK kinases at the N terminus of FZR118." (PMID 31015455, 2019).
microcephaly (1 paper, 2019). A congenital or acquired developmental disorder in which the circumference of the head is smaller than normal for the person's age and sex. "We found a de novo missense mutation in the Fzr1 gene (hg19; chr 19: 3527718; NM_001136198.1; c.560A>G) that generates an aspartate‐to‐glycine substitution (p.Asp187Gly) in a patient presenting microcephaly at birth, as revealed by the low OFD (< 3rd centile), and low body weight (< 3rd centile)." (PMID 31318984, 2019). "We found a novel missense (p.Asp187Gly) Fzr1 gene mutation (c.560A>G) in a heterozygous state in a 4‐year‐old boy, born from non‐consanguineous Spanish parents, who presents with severe antenatal microcephaly, psychomotor retardation, and refractory epilepsy." (PMID 31318984, 2019). "We previously found that genetic ablation of Fzr1 promotes the death of neural progenitor cells leading to neurogenesis impairment and microcephaly in mouse." (PMID 31318984, 2019). "Previously, we found that genetic ablation of Fzr1 promotes the death of neural progenitor cells leading to neurogenesis impairment and microcephaly in mouse." (PMID 31318984, 2019).
sarcopenia (1 paper, 2025). Progressive decline in muscle mass due to aging which results in decreased functional capacity of muscles. "Their statistical analyses identified that the FZR1 rs740681 SNP is significantly associated with sarcopenia risk." (PMID 40428823, 2025). "While FZR1 rs740681 represents a novel sarcopenia-associated variant, its evidence base is weakened by methodological constraints and indirect functional validation." (PMID 40428823, 2025).
tumor (14 papers, 2009 to 2025). "While previous studies implicated FZR1 in cell cycle, our competitive ubiquitination model introduces spatial-temporal regulation of substrate stabilization during tumor progression." (PMID 40346052, 2025). "Normal human fibroblasts undergo premature senescence after acute loss of FZR1, hinting at a built-in fail-safe mechanism against cancer development and the possible underlying molecular mechanism for the less frequently observed FZR1 loss in tumour cells." (PMID 27402801, 2016). "Thus, it is possible that loss of FZR1 occurs late in tumour development." (PMID 27402801, 2016). "Knockdown of FZR1 or inhibition of the APC/C with proTAME has been reported to enhance the sensitivity of a number of tumour cell lines to the topoisomerase II inhibitor etoposide, through an increase in APC/CFzr substrate TopIIα." (PMID 27655696, 2016). "Reduced expression of FZR1 is observed in several other tumours other than colon, including brain, liver, ovary, breast and prostate but it is also overexpressed in certain malignant tumours concomitantly with Emi1." (PMID 27402801, 2016). "We found that Cdh1 (FZR1, fizzy-related 1) was highly expressed in the tumor tissues." (PMID 35627188, 2022). "FZR1 has been described as both a tumor suppressor and oncoprotein." (PMID 36130950, 2022). "FZR1 has been reported as both a tumor suppressor and oncoprotein in a variety of cancer types." (PMID 32978372, 2020). "The result showed that FZR1 ko and cisplatin treatment significantly reduced tumor growth." (PMID 32978372, 2020). "Furthermore, to validate the functional role of FZR1 induced apoptosis by chemotherapy drugs, we performed the IHC for the patient tumor samples using cleaved caspase 3 antibody." (PMID 32978372, 2020). "In mice, Fzr1 heterozygosity results in the development of epithelial tumors, suggesting that Fzr1 may be a haploinsufficient tumor suppressor." (PMID 28049433, 2017). "Therefore, FZR1 has been proposed to be a putative haploinsufficient tumour suppressor." (PMID 27402801, 2016). "The study on incidence of tumor and development of carcinoma found that some DEPs indirectly inhibited the occurrence and development of MF, including CLU, GNAS, FZR1, and PKM." (PMID 33299887, 2020). "Therefore, in the future, it would be interesting to design anti-BRCA strategies by counterbalancing the activities of E2 and E3 ligases, for example, to maintain CCNF to suppress tumor-promoter RRM2 and/or inhibit FBXL8 and FZR1 to reduce their targeting of tumor-suppressor CCNF protein." (PMID 34201347, 2021).
cancer (8 papers, 2015 to 2024). A tumor composed of atypical neoplastic, often pleomorphic cells that invade other tissues. "Accumulation of Eg5 in cells expressing FZR1 carrying mutations in certain D- or KEN-box motifs causes cancer cell death." (PMID 27402801, 2016). "Nevertheless, SKP2, an FZR1 target, is up-regulated in many cancers." (PMID 27402801, 2016). "Future studies should determine whether expression levels of FZR1 or its proteolytic targets such as SKP2 provide prognostic markers for the response of cancer cells to CDK4/6 inhibitor treatment." (PMID 25562820, 2015). "Together, our data indicate that not only the mutant or WT status of Rb but also the expression levels of FZR1 and functional activity of the APC/CFZR1 E3 ligase will determine how cancer cells respond to CDK4/6 inhibitor treatment." (PMID 25562820, 2015). "Several substrates of PTP4A3 have been reported, including FZR1, Keratin 8, Integrin β1, and Leo l, where the phosphorylation levels of the substrates are regulated by PTP4A3, thereby affecting cancer-related signaling pathways and cancer progression." (PMID 38611852, 2024). "Thus, we propose that CCNF plays a cancer suppressor role, but its protein level is downmodulated in the disease, probably via FBXL8/FZR1-mediated degradation." (PMID 34201347, 2021).
neurodevelopmental disorder (1 paper, 2019). A behavioral and cognitive disorder with onset during the developmental period that involves impaired or aberrant development of intellectual, motor, or social functions. "To ascertain the possible translation of these findings in humans, we searched for mutations in the Fzr1 gene in 390 whole exomes sequenced in trio in individuals showing neurodevelopmental disorders compatible with a genetic origin." (PMID 31318984, 2019). "To ascertain the possible translation of our findings in humans, here we searched for mutations in the Fzr1 gene in 390 whole exomes sequenced in trio in individuals showing neurodevelopmental disorders compatible with a genetic origin." (PMID 31318984, 2019).
FZR1 also shares sentences with these, for which no sentence is quoted: infection (2 papers); agoraphobia (1); anxiety disorder (1); atherosclerosis (1); cardiac hypertrophy (1); Fibroadenoma (1); gastric cancer (1); generalized anxiety disorder (1); leukemia (1); male infertility (1); monoclonal gammopathy of undetermined significance (1); multiple myeloma (1); neuroblastoma (1); plasma cell dyscrasias (1); prostate carcinoma (1); severe aplastic anemia (1); social anxiety disorder (1); triple-negative breast carcinoma (1).